KIF18A (kinesin family member 18A)
Diseases named in the same sentence as KIF18A in open-access papers (continued):
Sharing a sentence is not in itself a finding about the gene and the disease.
acute myeloid leukemia (1 paper, 2022). Acute myeloid leukemia (AML) is a group of neoplasms arising from precursor cells committed to the myeloid cell-line differentiation. "The analysis of KIF18A expression in different tumour types from the TCGA database revealed that apart from acute myeloid leukemia (AML), kidney chromophobe (KICH), and testicular germ cell tumours (TGCT), KIF18A was highly expressed in nearly all the tumours when compared with normal tissue." (PMID 35591854, 2022).
astrocytoma (1 paper, 2019). "Additionally, we observed that the mRNA levels of KIF4A, KIF9, KIF18A, and KIF23 were elevated in LGG patients with a higher histological grade and astrocytoma histologic type than in those with a lower histological grade and histologic type, including oligoastrocytoma and oligodendroglioma." (PMID 30872592, 2019).
brain tumor (1 paper, 2022). "Specifically, KIF18A, as a risk factor, could significantly reduce the proliferation of most tumor cell lines (including brain tumor cell lines), while MN1, as a protective factor, could enhance the proliferation of most tumor cell lines (including brain tumor cell lines)." (PMID 35677036, 2022).
breast-infiltrating duct carcinoma (1 paper, 2024). "Therefore, this work aims to study the immunohistochemical expression and correlation of KIF18A and β-catenin in breast infiltrating duct carcinoma (IDC) and to find out their possible prognostic significance." (PMID 38195458, 2024). "Therefore, this work aims to study the immunohistochemical expression and correlation of KIF18A and β-catenin in breast-infiltrating duct carcinoma (IDC) and their relation to prognosis." (PMID 38195458, 2024).
cholangiocarcinoma (1 paper, 2019). A carcinoma that arises from the intrahepatic biliary tree (intrahepatic cholangiocarcinoma) or from the junction, or adjacent to the junction, of the right and left hepatic ducts (hilar cholangiocarcinoma). "Proteomic analysis indicated that KIF18A is a promising biomarker for the early diagnosis of cholangiocarcinoma (CCA)." (PMID 31392101, 2019).
colorectal adenocarcinoma (1 paper, 2024). The most common type of colorectal carcinoma. "To confirm changes in KIF18A localization in both chromosomally stable and unstable cell lines, we used diploid retinal pigment epithelial-1 (RPE1) cells and two chromosomally unstable cell lines, colorectal adenocarcinoma HT-29 cells and MDA-MB-231 cells." (PMID 38410188, 2024).
colorectal tumors (1 paper, 2025). "Targeting KIF18A enhanced response to anti-PD-1 immunotherapy through T cells in CIN+ colorectal tumors." (PMID 40175357, 2025). "In the present study, the potential influence of KIF18A on immune infiltration in CIN+ colorectal tumor was evaluated." (PMID 40175357, 2025). "In our study, KIF18A inhibition stimulated pro-inflammatory type I IFN signaling activation in CIN+ colorectal tumors, suggesting that KIF18A inhibition changed CIN+ tumors from “immune cold” to “immune hot”." (PMID 40175357, 2025). "To confirm the influence of KIF18A inhibition in antitumor immunity of CIN+ colorectal tumors, we also used another KIF18A inhibitor VLS-1488." (PMID 40175357, 2025). "Altogether, these results indicated that targeting KIF18A enhanced response to anti-PD-1 immunotherapy through T cells in CIN+ colorectal tumors." (PMID 40175357, 2025). "In our study, KIF18A inhibition by AM-1882 promoted cGAS-STING pathway activation in CIN+ colorectal tumors." (PMID 40175357, 2025). "Although previous studies reveal that KIF18A is a marker for prognosis and immunity of various cancers, it is uncertain if KIF18A inhibition may affect antitumor immunity of CIN+ colorectal tumors." (PMID 40175357, 2025). "However, KIF18A inhibition enhanced response to anti-PD-1 immunotherapy in CIN+ colorectal tumors in our study." (PMID 40175357, 2025). "Finally, targeting KIF18A enhanced PD-1 blockade efficiency in CIN+ colorectal tumors through T cells." (PMID 40175357, 2025). "Indeed, we found that KIF18A inhibition induced G2/M arrest of CIN+ colorectal tumors." (PMID 40175357, 2025). "Above all, our data indicated that KIF18A inhibition stimulated type I IFN signaling and cGAS-STING activation in CIN+ colorectal tumors." (PMID 40175357, 2025). "Mechanically, KIF18A inhibition stimulated type I IFN signaling and cGAS-STING activation in CIN+ colorectal tumors." (PMID 40175357, 2025). "KIF18A inhibition suppressed proliferation of Tregs and increased infiltration and activation of cytotoxic CD8+ T cells in CIN+ colorectal tumors." (PMID 40175357, 2025). "We found that KIF18A inhibition by a small inhibitor AM-1882 promoted immune infiltration and activation in CIN+ colorectal tumors." (PMID 40175357, 2025). "In summary, these results suggested that KIF18A inhibition promoted immune infiltration and activation in CIN+ colorectal tumors." (PMID 40175357, 2025). "Moreover, we found that KIF18A inhibition enhanced immune infiltration and activation in CIN+ colorectal tumors." (PMID 40175357, 2025). "In addition, KIF18A inhibition promoted immune infiltration and activation in CIN+ colorectal tumors." (PMID 40175357, 2025). "In our study, we found that KIF18A inhibition by AM-1882 enhanced infiltrating of CD45+ leukocytes, CD3+ T cells, CD3+CD8+ Cytotoxic T (Cyto T) cells, and decreased infiltrating of CD25+FoxP3+ regulator T (Treg) cells in CIN+ colorectal tumors." (PMID 40175357, 2025). "Indeed, KIF18A inhibition enhanced infiltration and activation of cytotoxic T cells and decreased the infiltration and proliferation of Treg cells, thus augmented antitumor immunity in CIN+ colorectal tumors." (PMID 40175357, 2025).
endometrial cancer (1 paper, 2023). Primary or metastatic malignant neoplasm involving the endometrium (mucous membrane that lines the endometrial cavity). "The mutation frequency of KIF18A is the highest in endometrial cancer." (PMID 36830695, 2023).
fibrosis (1 paper, 2024). the formation of excess fibrous connective tissue in an organ or tissue in a reparative or reactive process. "The results of qRT-PCR and Western blot showed that both mRNA and protein expression levels of KIF18A were lower in the liver samples of fibrosis models than in the control group mice." (PMID 38372748, 2024).
heart failure (1 paper, 2017). Inability of the heart to pump blood at an adequate rate to meet tissue metabolic requirements. "The modules related to cytoskeleton organization were detected specifically in heart failure arising from DCM, with increased KIF18A and TUBE1." (PMID 29160422, 2017).
Hepatic hemangioma (1 paper, 2014). A congenital vascular malformation in the liver composed of masses of blood vessels that are atypical or irregular in arrangement and size. "We further conducted immunohistochemical assay to detect KIF18A protein in 32 cases of HCC tissues, and found that 21 of 32 (65.6%) cancer tissues had KIF18A positive staining while only 8 of 32 (25.0%) ANLT and none of 8 normal liver tissues from hepatic hemangioma had KIF18A positive staining." (PMID 25431949, 2014).
Hernia (1 paper, 2009). "These genes may be involved in the estrogen receptor signaling pathway (KIF18A and NPTX1), the epithelial-mesenchymal transition (ELF5) and the collagen metabolism pathway (COL23A1), which are associated with the important molecular characteristics of hernia pathophysiology." (PMID 19287495, 2009).
liver fibrosis (1 paper, 2024). "To elucidate the molecular mechanisms underlying the involvement of KIF18A, we performed in vitro proliferation experiments and established a CCl4-induced liver fibrosis model." (PMID 38372748, 2024). "After validating the effect of KIF18A on LX-2 in vitro, we next determined the roles of KIF18A in liver fibrosis initiation and progression in vivo by evaluating the expression of fibrosis markers." (PMID 38372748, 2024). "In contrast, Col1A1, Timp1, and Tgfβ1 decreased, and Stat1 increased in both mRNA and protein levels following KIF18A overexpression in liver fibrosis models." (PMID 38372748, 2024). "The present findings demonstrate that overexpression of KIF18A alleviates the severity of liver fibrosis in mice." (PMID 38372748, 2024). "Overall, our findings indicate that KIF18A expression is reduced in human liver fibrosis, which promotes the activation of HSCs." (PMID 38372748, 2024). "We found that KIF18A significantly decreased in the human liver fibrosis tissues by qRT-PCR detection." (PMID 38372748, 2024). "Collectively, these results indicate that KIF18A expression is decreased in liver fibrosis tissues and HSCs." (PMID 38372748, 2024). "Considering the crucial role played by HSCs in the process of liver fibrosis, it is imperative to further ascertain the significant alterations in the expression of KIF18A within activated HSCs in fibrotic livers." (PMID 38372748, 2024). "In this study, we corroborated that KIF18A is expressed at low levels in both human and mice liver fibrosis tissues, indicating the potentially important role of KIF18A in the pathogenesis of liver fibrosis." (PMID 38372748, 2024). "Animal experiments demonstrated that knockdown of KIF18A could promote liver fibrosis, whereas overexpression of KIF18A alleviated liver fibrosis in a CCl4-induced mouse model." (PMID 38372748, 2024). "Subsequently, we evaluated the expression level of KIF18A in a mouse model of liver fibrosis to ascertain whether it was downregulated in a manner consistent with clinical samples." (PMID 38372748, 2024). "Indeed, further studies are necessary to determine the efficacy of targeting KIF18A for treating liver fibrosis." (PMID 38372748, 2024). "The downregulation of KIF18A expression in HSCs in liver fibrosis has been confirmed." (PMID 38372748, 2024). "Consistently, western blot showed that KIF18A protein expression was low in liver fibrosis." (PMID 38372748, 2024). "Therefore, we established a CCL4-induced mouse model of hepatic fibrosis and evaluated the effect of KIF18A overexpression on hepatic fibrosis in mice via intravenous injection of adenovirus." (PMID 38372748, 2024). "In addition, we examined the influence of KIF18A overexpression on hepatic fibrosis in mice models." (PMID 38372748, 2024). "Here, we demonstrate the downregulation of KIF18A in HSCs and liver fibrosis tissues, and identify its role in HSC activation and hepatic fibrosis induction through Akt/mTOR-signaling pathway." (PMID 38372748, 2024). "In the context of liver fibrosis, YY1 is aberrantly upregulated, resulting in the transcriptional suppression of KIF18A and its protein expression." (PMID 38372748, 2024). "The downregulation of KIF18A subsequently results in elevated p-AKT levels, ultimately activating the AKT/mTOR-signaling pathway and promoting the initiation and progression of liver fibrosis." (PMID 38372748, 2024). "In the present study, we observed that YY1 acts as a transcription repressor to inhibit the expression of KIF18A, and uncovered a hitherto undocumented mechanism by which YY1 regulates liver fibrosis in HSCs." (PMID 38372748, 2024). "In summary, our study sheds light on the YY1/KIF18A/TTC3-signaling pathway and its effects on AKT/TOR, providing a basis for future research into liver fibrosis treatment." (PMID 38372748, 2024). "Nevertheless, the role of KIF18A in benign liver diseases such as hepatic fibrosis is not well-established." (PMID 38372748, 2024).
liver fibrosis (continued). "By examining multiple pathways related to liver fibrosis, such as TGFβ/Smad pathway, Ras/ERK pathway, JAK/STAT pathway, and PI3K/AKT pathway, we found overexpression or knockdown of KIF18A only affected the expression of the effector proteins of PI3K/AKT pathway." (PMID 38372748, 2024). "Yet, it is still not entirely known how KIF18A contributes to liver fibrosis." (PMID 38372748, 2024).
lung squamous cell carcinoma (1 paper, 2020). "Association between Kif18A protein and clinical parameters in patients with lung squamous cell carcinoma." (PMID 31977917, 2020).
mononucleosis (1 paper, 2022). "KIF18A is a form of mononucleosis characterized by monocytosis (mononucleosis) and monocytosis (mononucleosis)." (PMID 35464837, 2022).
papillary renal cell carcinoma (1 paper, 2019). A rare subtype of renal cell carcinoma, arising from the renal tubular epithelium and showing a papillary growth pattern, which typically manifests with hematuria, flank pain, palpable abdominal mass or nonspecific symptoms, such as fatigue, weight loss or fever. "We identified 5 mRNAs that are associated with the survival of patients with papillary renal cell carcinoma,namely CCNB2, IGF2BP3, KIF18A, PTTG1, and BUB1 in the training set." (PMID 30822312, 2019). "In general, the 5-mRNA (CCNB2, IGF2BP3, KIF18A, PTTG1, and BUB1) were identified and validated, which can predict papillary renal cell carcinoma patient survival." (PMID 30822312, 2019).
cancer (57 papers, 2014 to 2025). A tumor composed of atypical neoplastic, often pleomorphic cells that invade other tissues. "KIF18A is overexpressed in various cancers, including breast tumors, and has been associated with cell proliferation, cell invasion, and poor survival." (PMID 40227811, 2025). "A flurry of recent studies has implicated KIF18A as a tractable therapeutic vulnerability specifically in cancers with aneuploidy, CIN, weakened APC/C activity, and SAC persistence." (PMID 40002279, 2025). "While loss of Kif18A function seems to be tolerated by euploid cells, it is crucial for the survival of certain aneuploid cancers, revealing its strong potential as an antitumor therapeutic target." (PMID 39610707, 2024). "Overexpression of KIF18A has been reported in a subset of human cancer types (for example, breast and colorectal) and is associated with tumor aggressiveness." (PMID 38151625, 2024). "Specifically, KIF18A is required for chromosomally unstable tumor cells for proliferation and exhibits association with pan cancer survival across multiple cohorts." (PMID 39416165, 2024). "Researchers found that the expression of KIF18A was positively associated with regulatory genes of RNA methylation in certain types of cancer." (PMID 39518001, 2024). "To further explore cancer-specific mitotic vulnerabilities associated with chromosomally unstable aneuploid cells, we focused our investigation on the kinesin motor protein KIF18A." (PMID 38151625, 2024). "We discovered a high diagnostic value of KIF18A expression in 20 kinds of cancers (AUC > 0.8), indicating that KIF18A can play a crucial role in tumor diagnosis." (PMID 36830695, 2023). "Cancer cells that are aneuploid, tetraploid or have a chromosomal instability phenotype are extremely vulnerable to the loss of KIF18A, as compared to euploid cancer cells." (PMID 37639469, 2023). "Recently, three papers reported that CIN or aneuploid cancer cells are vulnerable to Kif18A depletion, which causes spindle defects such as multipolar spindle formation." (PMID 34572757, 2021). "Several studies have shown that KIF18A is highly expressed in most malignant tumours (renal carcinoma, breast cancer, etc.)and is associated with cell proliferation, tumour staging and the prognosis of tumour cells." (PMID 29466986, 2018). "Moreover, the sensitivity of aneuploid cancer cells to chemical Kif18A inhibition appears to be linked to their capacity to delay mitosis exit through an efficient SAC response." (PMID 39610707, 2024). "This may help explain why CIN cancers have been shown to be, on average, more sensitive to KIF18A loss." (PMID 38279026, 2024). "Interestingly, KIF18A expression had a positive association with Th2 for 33 cancers in the TCGA database." (PMID 36830695, 2023). "KIF18A expression had a positive association with T helper cells in 31 cancers." (PMID 36830695, 2023). "KIF18A has been implicated in many cancer types, including renal and breast cancer." (PMID 33753726, 2021). "Kif18a is a kinesin protein involved in chromosomal stability, low expression of kinesin proteins has been associated with cell proliferation of chromosomally unstable genes and is a candidate target for cancer treatment." (PMID 35087569, 2021). "Potential role KIF18A is associated with cell division and checkpoint activation in cancer progression, but this gene might be responsible for cell division and checkpoint activation in pituitary prolactinoma." (PMID 33709028, 2021).